AR (androgen receptor)
Diseases named in the same sentence as AR in open-access papers (continued):
Sharing a sentence is not in itself a finding about the gene and the disease.
prostate carcinoma (continued). "The RNA-Binding Motif Protein 39 (RBM39) splicing factor stimulates the inclusion of a cryptic exon containing a stop signal in the androgen receptor (AR) gene, giving rise to the oncogenic variant AR-V7, the best-characterised AR variant, in prostate cancer." (PMID 38893242, 2024). "One study had previously indicated that depleting DDX39A and DDX39B results in decreased expression of alternatively spliced variants of the androgen receptor (AR) in prostate cancer cells." (PMID 38801080, 2024). "AR expression is a key driver in the development and progression of prostate cancer, and EVs have been implicated in transferring ARs between cells." (PMID 38730670, 2024). "The androgen receptor (AR) degrader, ARV-110, has demonstrated therapeutic responses in prostate cancer patients with both wild-type AR and those harboring AR T878A and H875Y mutations." (PMID 38844984, 2024). "To gain experimental support for RNA secondary structure models, we employed targeted DMS-MaPseq in 22Rv1 cells to analyze both the longest isoform, AR-FL (FL), as well as the prostate cancer-associated truncated isoform, AR-V7 (V7)." (PMID 38554103, 2024). "The biology of the AR has been integrally linked to metabolic reprogramming and transcriptional changes in prostate cancer, and here we show an association of this critical receptor with endosomes–lysosomes and its intra- and intercellular transport." (PMID 39858418, 2024). "Most patients with prostate cancer (4/6) had alterations in AR, including copy number changes and a T878A variant of the LBD." (PMID 38086998, 2024). "In prostate cancer cells, AR regulates a transcriptional program associated with growth, luminal differentiation, and survival." (PMID 39117800, 2024). "Over the past decade, various mRNAs from C-terminally truncated, constitutively active AR-variants have been identified in cell lines, patient xenografts and primary prostate cancer tissue specimens." (PMID 38500100, 2024). "Of particular interest is AR’s involvement in prostate cancer, which is the second leading cause of cancer related death among men in the United States." (PMID 38554103, 2024). "The androgen receptor (AR) is a crucial player in various aspects of male reproduction and has been associated with the development and progression of prostate cancer (PCa)." (PMID 38238739, 2024). "Patients receiving radical radiotherapy for very high‐risk/locally advanced prostate cancer should receive 24 months of Abiraterone + Prednisolone (or alternative novel Androgen Receptor Targeted Agent as evidence emerges) in addition to ADT?" (PMID 39539560, 2024). "They present evidence that prostate cancer tumor cells differentiate into AR pathway independent lineages that are associated with an overexpression of Wntless, a Wnt transporter that promotes Wnt signalling." (PMID 38607014, 2024). "Phase 3 (ARMOR3-SV) lasted from June 2015 to November 2016, and it was a study of galeterone compared to enzalutamide in men expressing androgen receptor spice variant-7 mRNA (AR-V7) in metastatic castration-resistant prostate cancer." (PMID 39598525, 2024). "Of the RECWAS‐identified peaks, 10 out of 18 AR peaks and 16 out of 32 H3K27ac peaks mapped to prostate cancer susceptibility genes in the DisGeNET database." (PMID 39099406, 2024). "This cluster has been reported to be regulated by AR in prostate cancer in association with autophagy." (PMID 38339416, 2024). "AR-V7, a constitutively active AR variant, induces arginine vasopressin receptor 1a expression in prostate cancer cells, which promotes CREB activation and castration resistance." (PMID 38233872, 2024). "The androgen receptor (AR) is a targetable oncogenic driver of prostate cancer; however, aberrant splicing of AR-encoding mRNA can lead to resistance against available treatments." (PMID 38329136, 2024).
prostate carcinoma (continued). "Meanwhile, the activity of androgen receptor (AR), a member of the nuclear receptor superfamily, is well known to be associated with the outgrowth of even castration-resistant prostate cancer." (PMID 39000396, 2024). "In prostate cancer, the generation of C-terminally truncated AR-variants (AR-Vs) is predominantly driven by the splicing of cryptic exons, exon skipping or genetic rearrangements." (PMID 38500100, 2024). "For example, the dysregulation, transcriptional activity, and chromatin interactions of the androgen receptor (AR) are critical for the activation of gene pathways associated with tumor progression in prostate cancer (PCa)." (PMID 39682146, 2024). "Another example of iRGD peptide utilization is the respective functionalization of liposomes with encapsulated antisense oligonucleotides (ASOs) against the androgen receptor (AR) gene and its splice variants for the treatment of prostate cancer." (PMID 39594723, 2024). "AR signalling is linked to the onset and progression of prostate cancer (PCa), where it becomes a primary driver of tumour growth." (PMID 38969865, 2024). "Darolutamide, an androgen receptor inhibitor, has been approved by the Food and Drug Administration (FDA) for the treatment of prostate cancer (PCa), especially for patients with androgen receptor mutations." (PMID 39309439, 2024). "Considering that AR immunostaining has a diagnostic, potential prognostic, and predictive role in other tumors apart from prostate cancer, a comprehensive and highly standardized study analyzing a large number of tumors from different tumor entities is needed." (PMID 38790919, 2024). "In contrast, after 24 h of treatment with UBX‐390, the levels of proteins associated with the AR and prostate cancer signaling pathways were downregulated compared to those observed after treatment with dimethyl sulfoxide (DMSO)." (PMID 38958553, 2024). "Aberrant transcriptional activation of the androgen receptor (AR) is a predominant cause of prostate cancer (PCa), including both in the initial and androgen‐independent stages." (PMID 39470578, 2024). "JAK/STAT signaling has been linked to increased plasticity in AR-low prostate cancer, with the potential to progress further to DNPC and NEPC." (PMID 39027480, 2024). "P-gp overexpression as well as loss, mutation or variant expression of AR are among the main mechanisms of prostate cancer therapy resistance." (PMID 38783016, 2024). "We then questioned if PTEN or androgen receptor (AR) status can affect LD accumulation associated with PIM1 in prostate cancer." (PMID 38097734, 2024). "Of patients with prostate cancer whose ctDNA data were available, 4/6 (67%) had AR alterations (one single nucleotide variant and three copy number variants)." (PMID 38086998, 2024). "Over 20 different androgen receptor variants (AR-Vs) have been identified in prostate cancer cell lines and biopsy specimens of CRPC." (PMID 39199550, 2024). "Somatic pathogenic variants of the AR gene have been described in both patients with androgen insensitivity syndrome and prostate cancer." (PMID 39596257, 2024). "Through mechanisms not well understood, specific mutations in the genes of the AR signaling pathway are known to ultimately promote the growth and proliferation of prostate cancer." (PMID 38542265, 2024). "The androgen receptor (AR) is the main driver in the development of castration‐resistant prostate cancer, where the emergence of AR splice variants leads to treatment‐resistant disease." (PMID 38605607, 2024). "Previous studies indicated that the expression of the androgen receptor splicing variant ARV7 in CTCs of prostate cancer patients is associated with innate and acquired resistance to the androgen receptor (AR)-targeted therapies." (PMID 36707540, 2023).
prostate carcinoma (continued). "In prostate cancer, hsa-miR-1207-5p is downregulated and associates with the androgen receptor via FNDC1, a protein that contains a conserved protein domain of fibronectin and it is upregulated in this type of cancer." (PMID 38146340, 2023). "For example, the conversion from CRPC to neuroendocrine-type prostate cancer usually leads to the loss of AR and responsiveness to AR-targeted therapies." (PMID 37175938, 2023). "Downstream molecules of the β-catenin pathway have also been reported to act as co-activators of the androgen receptor which itself is an oncogene associated with prostate carcinoma." (PMID 38348349, 2023). "The aberrant activation of androgen receptor signaling pathways (AR) is linked with castrate-resistant prostate cancer." (PMID 37858151, 2023). "The tyrosine phosphorylation of DDX5 at Y593 caused by c-Abl contributes to the coactivation of androgen receptor and tumorigenesis in prostate cancer." (PMID 36593242, 2023). "We performed ~1400X targeted NGS designed to capture AR coding sequences and recurrent prostate cancer mutations and in total detected seven unique non-synonymous functionally-active mutations within AR coding regions." (PMID 37563129, 2023). "Androgen receptor signaling is active in tumor‐associated macrophages (TAMs) and inhibits the transcription of IL‐1β in prostate cancer." (PMID 37092583, 2023). "The high expression of CBP and p300 is associated primarily with the AR signature in prostate cancer." (PMID 37511059, 2023). "Much of the focus of alternative splicing research in prostate cancer has been on investigating alternatively spliced isoforms encoded by the androgen receptor gene (AR) itself." (PMID 37752235, 2023). "AR genetic alterations including mutations and amplifications are observed in prostate cancer as well as alternative splicing events." (PMID 36937425, 2023). "For instance, RNA splicing factors have been found to promote the expression of the androgen receptor and its variants, which is crucial for the progression of prostate cancer." (PMID 37559353, 2023). "Niclosamide effectively downregulates androgen receptor variants (AR-Vs) for treating enzalutamide and abiraterone-resistant prostate cancer." (PMID 37242518, 2023). "Previous researches show that germline mutations of AR gene are associated with the incidence of prostate cancer (PCa) and the development of breast cancer." (PMID 38023196, 2023). "Prostate cancer cells can develop mechanisms to resist androgen deprivation therapy, such as AR overexpression, AR mutations, alterations in AR coregulators, increased steroidogenic signaling pathways, outlaw pathways, and bypass pathways." (PMID 37894414, 2023). "Reciprocal feedback regulation of PI3K signalling and androgen receptor signalling has been shown in PTEN deficient castration-sensitive prostate cancer where combined inhibition of AKT and androgen receptor signalling was particularly efficacious." (PMID 36708693, 2023). "For example, PD-L1 for monitoring patients undergoing immunotherapy, androgen receptor splice variant 7 (ARv7) for emergence of therapeutic resistance in prostate cancer, and assessing biomarkers such as EGFR, HER2 or PD-L1 in esophageal cancer." (PMID 37051527, 2023). "Castration-resistant prostate cancer often develops in response to continued drug treatment and is characterized by mutations in the androgen receptor." (PMID 37046780, 2023). "As discussed in the earlier section, these drugs target the androgen receptor or its activation, and both have been shown to be clinically effective, particularly in high-risk prostate cancer patients." (PMID 37273124, 2023). "The binding of 14-3-3 to the NTD of AR, which remains present in the AR splice variants, provides an alternative entry point of targeting AR in drug- and castration-resistant patients with prostate cancer." (PMID 37224961, 2023).
prostate carcinoma (continued). "During the castration-resistant phase of prostate cancer, AR is reactivated through several mechanisms, including AR amplification and mutation, as well as activation of ARs through other signaling pathways." (PMID 36900309, 2023). "Alterations in de novo lipogenesis and fatty acid catabolism are consistently reported during prostate cancer development and progression in association with androgen-receptor signaling." (PMID 37444583, 2023). "Although prostate cancer is initially often successfully targeted with androgen deprivation therapy or AR antagonists such as enzalutamide, drug- and castration-resistant AR mutants or splice variants are often developed within patients with prostate cancer." (PMID 37224961, 2023). "The gain-of-function T877A mutation expands the range of activating ligands for the AR and assigns a specific key castration-resistant prostate cancer pathway in these cells." (PMID 36829927, 2023). "Along the same line, Jillson and colleagues showed that co-suppression of MAP3K7 and CHD1 causes androgen-independent growth of prostate cancer cells and promotes resistance to AR inhibitor enzalutamide." (PMID 36776288, 2023). "Recently, it has become a standard treatment to use androgen receptor signaling inhibitors (ARSIs) or/and docetaxel in addition to medical or surgical castration from the initial treatment, according to the risk of prostate cancer." (PMID 37174127, 2023). "Among various causes of prostate cancer androgen receptor (AR) signaling, PTEN/PI3K/AKT/mTOR pathway, IL6/STAT3 and STAT5a/b are the most common pathways involved in prostate cancer cell survival and resistance." (PMID 36648960, 2023). "This technology can identify the androgen receptor splice variant 7 (ARV7) in circulating tumor cells (CTCs) for therapy resistance diagnosis in prostate cancer as well as visualize microRNA and noncoding RNA." (PMID 36707540, 2023). "Overexpression of androgen receptor (AR) is the primary cause of castration-resistant prostate cancer, although mechanisms upregulating AR transcription in this context are not well understood." (PMID 36727462, 2023). "A major limitation of current prostate cancer pharmacotherapy approaches is the inability of these compounds to target androgen receptor variants or mutants that develop during prostate cancer progression." (PMID 37046780, 2023). "Neuroendocrine prostate cancer (NEPC) is a sub-variant of aggressive prostate cancer that rarely arises de novo, but most frequently emerges after androgen receptor (AR)-targeted therapies for prostate adenocarcinoma." (PMID 37065756, 2023). "The use of mRNA sequencing from biopsies of prostate cancer revealed that the expression of these molecules is associated with AR mRNA expression in early prostate cancer as well as in metastatic castration-resistant prostate cancer." (PMID 37511059, 2023). "As a result, the combined inhibition of MAPK and AR pathways provides a potential therapeutic effect in BRAF-mutated prostate cancer patients." (PMID 36969009, 2023). "Further studies are needed to better explain the molecular mechanisms underlying the anticancer effects promoted by ALA in both AR+ and AR− prostate cancer cells." (PMID 38069431, 2023). "Increased skipping of FLNB exon 30 (an exon normally activated by the AR-ESRP axis in prostate cancer), is tightly linked to the development of metastases in breast cancer." (PMID 37752235, 2023). "Two other studies have revealed a tumor suppressor role for NDRG1 in prostate cancer in association with the role of this protein in modulation of AR activity." (PMID 37249826, 2023). "Since the transition of prostate cancer into CRPC is irreversible and is associated with AR-mediating androgen signaling, we focused on the functions of AR and its co-regulators in prostate cancer development in this review." (PMID 37025180, 2023).
prostate carcinoma (continued). "The critical association of MEN1 with Androgen receptor signalling pathway and its oncogenic role in prostate cancer is well documented." (PMID 37437063, 2023). "Evidence from this study demonstrated that there is an association between AR genotype and the risk of PC, and that AR-CC genotype increases an individual's susceptibility to prostate cancer." (PMID 36824501, 2023). "Duplication of an enhancer region near the androgen receptor (AR) locus has been found in advanced prostate cancer that causes therapeutic resistance." (PMID 37548349, 2023). "Enzalutamide, an anti-androgen, targets AR’s ligand-binding domain to improve survival in patients with prostate cancer; thus, AR overexpression is associated with a worse prognosis." (PMID 37444447, 2023). "Annually, more than 350,000 deaths are associated with prostate cancer, making the disease one of the leading causes of cancer-related death in men, and the androgen receptor (AR) is believed to drive hormone dependency of prostate cancer." (PMID 36733714, 2023). "WNT4 located in 1p36 and the induction of WNT4/TCF7L1 resulted in increased malignancy in prostate cancer that was linked to dysregulation of androgen receptor signalling and activation of the IL‐8/CXCR2 pathway." (PMID 37378426, 2023). "Androgen receptor (AR) splice variants (AR-Vs) have been discussed as a biomarker in prostate cancer (PC)." (PMID 37016463, 2023). "On the basis of these findings, we anticipated that AR splice variant and structural variant expression should be inhibited in prostate cancer with fimepinostat treatment as the primary mode of AR inhibition is transcriptional suppression." (PMID 37823778, 2023). "Since ARv7 expression contributes to Enz-resistance of CRPC, we used 22Rv1, which is a well-studied Enz-resistant prostate cancer cell line that expresses both full-length AR and AR splice variants including ARv741,42." (PMID 37794090, 2023). "Either loss of AR expression/activity or deletion of the ARE1 sequence can restore NK1R expression in prostate cancer cells." (PMID 37385990, 2023). "It is known that sulforaphane increases NRF2 activity causing a decrease in full-length androgen receptor (AR-FL) expression in prostate cancer cell lines sensible to ADT." (PMID 37296999, 2023). "Multiple studies have demonstrated the importance of androgen receptor (AR) splice variants (SVs) in the progression of prostate cancer to the castration-resistant phenotype and their utility as a diagnostic." (PMID 37626712, 2023). "The associated preclinical studies in prostate cancer treatment have also increased, including targeted AR signaling pathways (including AR variants) and non-AR signaling pathways." (PMID 37095108, 2023). "The ability of certain PROTACs to effectively degrade these AR variants highlights their potential as a promising strategy for overcoming treatment resistance in prostate cancer and other diseases." (PMID 37175108, 2023). "A recent meta-analysis also concluded that the use of androgen receptor inhibitors is associated with an increased risk of falls and fractures in patients with prostate cancer." (PMID 37025594, 2023). "In advanced prostate cancer and castrate-resistant disease state, a class of mutations in the androgen receptor has been identified with a complete loss of the ligand binding domain and functionally constitutively active without any need for androgen ligands." (PMID 36671680, 2023). "The discovery of new drugs targeting CRPC is hampered by the limited molecular understanding of how AR binds mutated DNA sequences, frequently observed in prostate cancer, and how mutations within the protein and DNA regulate AR-DNA interactions." (PMID 36674785, 2023). "The association of the androgen/AR complex with the senescence program was first made in androgen-responsive prostate cancer cells and human dermal papilla cells." (PMID 37190127, 2023).